HOXC5 (homeobox C5)
Description:
Sequence-specific transcription factor which is part of a developmental regulatory system that provides cells with specific positional identities on the anterior-posterior axis.
Synonyms: HOX3D; CP11; HOX3
Tractability: PROTAC: ubiquitination databases record sites on it.
Gene: Protein-coding gene on chromosome 12 (54,033,050 to 54,035,361, forward strand). Ensembl gene ENSG00000172789.
Subcellular location: Nucleus
Subcellular location (Human Protein Atlas): Nucleoplasm; Cell Junctions
Gene Ontology:
Molecular function: protein binding; DNA-binding transcription factor activity; DNA-binding transcription factor activity, RNA polymerase II-specific; RNA polymerase II cis-regulatory region sequence-specific DNA binding; DNA binding
Biological process: anterior/posterior pattern specification; regulation of transcription by RNA polymerase II; regulation of DNA-templated transcription
Cellular component: nucleoplasm; chromatin; nucleus
Genetic constraint (gnomAD): Loss-of-function variants: 19 observed, 19.27 expected, observed/expected ratio (o/e) 0.99, 90% interval 0.69 to 1.45. The upper end of that interval is the gene's LOEUF score, 1.45, which puts it in group 5 of 6, group 1 being the genes least tolerant of losing a copy. Missense variants: 330 observed, 306.25 expected, observed/expected ratio (o/e) 1.08, 90% interval 0.98 to 1.18. Synonymous variants: 124 observed, 120.1 expected, observed/expected ratio (o/e) 1.03, 90% interval 0.89 to 1.2.
Homologues: Orthologues: chimpanzee HOXC5 (100% identical), macaque HOXC5 (99% identical), mouse Hoxc5 (99% identical), pig HOXC5 (99% identical), rat Hoxc5 (99% identical), guinea pig HOXC5 (99% identical), dog HOXC5 (96% identical), tropical clawed frog hoxc5 (72% identical), zebrafish hoxc5a (51% identical). Paralogues in human: HOXB5 (40% identical), HOXA5 (39% identical), HOXC4 (37% identical), HOXD4 (37% identical), HOXB4 (36% identical), HOXA4 (34% identical), HOXB6 (33% identical), HOXC6 (33% identical), HOXA6 (32% identical), HOXB7 (32% identical), HOXA7 (31% identical), HOXB8 (31% identical), and 30 more.
Diseases named in the same sentence as HOXC5 in open-access papers:
HOXC5 is named in the same sentence as 29 diseases in open-access papers, as found by Europe PMC text mining. Sharing a sentence is not in itself a finding about the gene and the disease. The quoted sentences say what the papers report.
glioma (3 papers, 2023 to 2025). A benign or malignant brain and spinal cord tumor that arises from glial cells (astrocytes, oligodendrocytes, ependymal cells). "HOXA6 and HOXC5 IHC staining was weak in the normal brain tissues, while glioma tissue exhibited strong HOXA6 and HOXC5 IHC staining." (PMID 37547473, 2023). "Additionally, the mIF in HPA revealed that HOXC4, HOXC5, and HOXC6 proteins were primarily expressed in nucleoplasm in the glioma cell line U-251MG." (PMID 37547473, 2023).
prostate carcinoma (3 papers, 2009 to 2024). A carcinoma that arises from epithelial cells of the prostate gland. "An unbiased analysis of DNA methylation and gene expression data using a large set of tumors from TCGA identified HOXB13, HOXC4, HOXC5, and HOXC6 in the set of the top 10 transcription factors whose expression is linked to the creation of newly active distal regulatory elements in prostate cancers." (PMID 30866492, 2019). "Some of these genes have known functions in prostate cancer, such as FGFR1, BCL2, HOXC5, HOXA4, TWIST1, EZH2, KLF4, CTGF." (PMID 19262738, 2009). "Specifically, it is not clear if HOXC4, HOXC5, and HOXC6 are all drivers of prostate cancer or if the three proteins are all upregulated due to genomic proximity, but only one is a direct regulator of tumorigenesis." (PMID 30866492, 2019).
bladder cancer (2 papers, 2023 to 2025). "In cisplatin-resistant bladder cancer cell lines, FLRT2, HOXC5, SCD, GRM7, HMGA1, ETV7, and SCO2 were highly expressed, while EMP1, SERPINA6, and ZNF124 exhibited lower expression levels." (PMID 39744172, 2025). "The expression of HOXC4, HOXC5, HOXC6, and HOXC11 was detected in 60%, 86%, 100%, and 80% of bladder cancer tissues, respectively." (PMID 37627900, 2023). "Four genes (HOXC4, HOXC5, HOXC6, and HOXC11) located at the HOX C locus as well as one gene (HOXD11) located at the HOX D locus were not expressed in normal bladder tissues but expressed in most bladder cancer tissues." (PMID 37627900, 2023).
clear cell renal cell carcinoma (2 papers, 2023 to 2025). "HOXC5, specifically enriched in tumor cells, has been significantly associated with poor prognosis in clear cell renal cell carcinoma (ccRCC)." (PMID 37547473, 2023).
testicular germ cell tumor (2 papers, 2018 to 2019). A germ cell tumor arising from the testis. "Analysis of RNA-Seq data set from 33 TCGA cancer types indicated that reduced HOXC5 expression contributes to the activation of hTERT in human cancers such as thymoma and testicular germ cell tumors." (PMID 29311615, 2018). "Analysis of RNA-Seq data set from 33 TCGA cancer types suggests that reduced HOXC5 expression contributes to the activation of hTERT in human cancers such as thymoma and testicular germ cell tumors." (PMID 29311615, 2018). "In thymoma and testicular germ cell tumor (TGCT), expression of HOXC5 plays key roles in suppressing the activity of hTERT, a protein subunit of telomerase, which is often abnormally activated and involved in proliferation in cancer." (PMID 31013831, 2019). "However, only thymoma (THYM, Spearman r = −0.23, p = 0.02, ) and testicular germ cell tumor (TGCT, Spearman r = −0.32, p < 0.001), which originated from telomerase-rich tissues, showed strongest inverse correlation between HOXC5 and hTERT expression." (PMID 29311615, 2018).
asthma (1 paper, 2021). "Further, in a study using Hox5 compound null alleles (Hoxa5+ ⁣/−; Hoxb5–/–; Hoxc5+ ⁣/−), mice present with an increased Th2 cells response and exacerbated lung tissue pathology in asthma models." (PMID 34901011, 2021).
breast tumors (1 paper, 2023). "HOXC5 is expressed in quiescent endothelial cells (EC); its expression is diminished or absent in active angiogenic EC found in association with breast tumors." (PMID 37547473, 2023).
cognitive decline (1 paper, 2024). "HOXC5- and HOXC6-associated DMP cg08254359 was significantly correlated with the cognitive decline speed, namely, mPACCdigit_speed (r = −0.12, p = 2.76E-02) and mPACCtrailsB_speed (r = −0.12, p = 2.92E-02)." (PMID 38298218, 2024).
Hypertension (1 paper, 2023). The presence of chronic increased pressure in the systemic arterial system. "Multiple HOXC genes: HOXC-AS1-3, HOXC4, HOXC5, HOCX6, HOXC8, HOXC9 and HOXC10 were also shared between subsets of GORD, hypertension and precordial pain." (PMID 37410157, 2023).
medulloblastoma (1 paper, 2023). A malignant, invasive embryonal neoplasm arising from the cerebellum. "Based on the single-cell data of 13 medulloblastomas, we observed that three HOXC genes (HOXC4, HOXC5, and HOXC6) were expressed in neurons and neuroepithelial cells, specifically within the WNT and Group 3 subtypes of medulloblastoma." (PMID 37547473, 2023).
myeloma (1 paper, 2021). "Specifically, we found that healthy MSCs exposed to MM cells underwent gains (HOXA9, ACVR2A, EBF2) and losses (HOXA2, HOXA3, HOXC5) of DNA methylation in the direction of those observed for MSCs from myeloma patients." (PMID 33462210, 2021).
neuroblastoma (1 paper, 2024). Neuroblastoma (NB) is the most common solid, extracranial childhood tumor. "RNA sequencing results showed a synergistic induction of genes associated with RA signaling (RARB, RARG), neuronal differentiation (HOXC5, PBX1), and chromatin remodeling (RYBP, JADE2), which are positively correlated with favorable prognosis in neuroblastoma." (PMID 39711563, 2024).
ovarian carcinoma (1 paper, 2017). A malignant neoplasm originating from the surface ovarian epithelium. "Specifically, upregulation of HOXA10 and HOXB3 genes and downregulation of HOXC5 were significantly associated with unfavorable survival outcomes in patients with ovarian cancer." (PMID 29050303, 2017). "In conclusion, dysregulated expression of the HOXA10, HOXB3, and HOXC5 genes was significantly associated with favorable or unfavorable overall survival in a large ovarian cancer cohort from TCGA." (PMID 29050303, 2017).
renal carcinoma (1 paper, 2022). A carcinoma arising from the epithelium of the renal parenchyma or the renal pelvis. "As we expected, both of these drugs significantly decreased the proliferation rate of tumor cells and the expression levels of HOXC5, ISL1, and VENTX in two renal cancer cell lines." (PMID 35853872, 2022).
cancer (9 papers, 2018 to 2024). A tumor composed of atypical neoplastic, often pleomorphic cells that invade other tissues. "Loss of HoxC5-mediated hTERT repression may be an alternative mechanism in the activation of hTERT expression in human cancers, especially for cancers derived from tissues, such as thymus and testis, which contain telomerase-positive progenitor cells/stem cells." (PMID 29311615, 2018). "miR-615 is located in the intron of humans or mice’s HOXC5 gene, and plays a pivotal role during cancer development and progression." (PMID 35883696, 2022). "HOXC5 transcription factor is also involved embryonic development; however, the deregulation of HOXC5 has been shown to contribute to activation of the TERT gene in human cancers." (PMID 35629968, 2022). "On the other hand, some HOX genes, including HOXC5, act as a proliferation inhibiting gene in cancer." (PMID 31013831, 2019). "We established xenograft models to further validate the effects of miR-615-3p and HoxC5 on cancer cell growth in vivo." (PMID 29311615, 2018). "We observed significant correlation (Spearman’s correlation, P < 0.05) in ~40% (n = 13/33) of the cancer types between HOXC5 and hTERT expression." (PMID 29311615, 2018). "Here we have identified roles for HoxC5 and miR-615-3p in the negative regulation of hTERT in cancer cells and during differentiation of pluripotent stem cells." (PMID 29311615, 2018). "Further, overexpression of miR-615-3p and HoxC5 suppress cancer cell growth both in vitro and in vivo in mouse xenograft model." (PMID 29311615, 2018). "We examined the expression of hTERT and HOXC5 mRNA using RNA-Seq data in 33 cancer types from the TCGA consortium." (PMID 29311615, 2018). "Understanding how miR-615-3p and HoxC5 mediate the cell-specific repression of hTERT and its implication in telomerase activation in human cancers can provide new avenues and targets for anti-cancer therapy." (PMID 29311615, 2018). "TERT mRNA levels were drastically reduced in cancer cells which transiently overexpressed PBX4 or MEIS3 combinatorially with HOXC5 to transcriptionally repress TERT." (PMID 29614790, 2018). "HOXC5 over-expression resulted in significantly reduced hTERT, low telomerase activity, and sequential reduction of telomeres in different cancer cells." (PMID 29614790, 2018). "This is the case both in human cancer cell lines and during differentiation of pluripotent cells, in which the expression of HOXC5 and miR-615-3p is suppressed but significantly activated during cell differentiation compared to the expression of hTERT in differentiated cells." (PMID 32605009, 2020). "However, increased telomerase expression has been observed in more than 85% of cancers, which can be dramatically reduced by overexpression of HOXC5 and miR-615-3p." (PMID 32605009, 2020). "In addition, overexpression of HOXC5 and miR-615-3p in human cancer cells significantly inhibits hTERT expression and suppresses cancer cell growth both in vitro and in vivo." (PMID 29311615, 2018). "Next, we wanted to examine the correlation of hTERT and HOXC5 expression in human cancers." (PMID 29311615, 2018). "The expression of hTERT and HOXC5 in different human cancers has been wide spread." (PMID 29311615, 2018). "Deregulation of HOXC5 and mir-615-3p expression may contribute to the activation of hTERT in human cancers." (PMID 29311615, 2018). "Overexpression of HOXC5 in PC-3 also resulted in rapid telomere shortening and induction of telomere-dysfunction induced foci (TIFs), which may contribute to the inhibition of cancer cell proliferation." (PMID 29311615, 2018). "Genes involved in angiogenesis (HOXA2, HOXC5), genome instability (HOXC5, HOXC11), deregulating cellular energetics (HOXA4, HOXC5), and metastasis (HOXA2) were all up-regulated in ecDNA(+) cancers." (PMID 38896472, 2024).
cancer (continued). "To study the potential role of miR-615-3p and HoxC5 in cancer cell proliferation, we transduced PC-3 cells with lentivirus expressing GFP, HOXC5, or mir-615-3p alone, or HOXC5 and mir-615-3p in combination." (PMID 29311615, 2018).
tumor (8 papers, 2018 to 2025). "We identified tumor cell-specific regulatory programs mediated by four key transcription factors (TFs) (HOXC5, VENTX, ISL1, and OTP), and these TFs have prognostic significance in The Cancer Genome Atlas (TCGA) database." (PMID 35853872, 2022). "PC-3 cells which individualistically expressed HOXC5 or miR-615-3p, or co-expressed miR-615-3p and HOXC5 were inoculated subcutaneously into immuno-compromised mice for detailed analysis of tumor growth." (PMID 29614790, 2018). "We further confirmed that knocking down two TFs (HOXC5 and ISL1) strongly reduced tumor growth in the xenograft mouse models." (PMID 35853872, 2022). "In this study, we revealed several pivotal regulatory TFs (HOXC5, ISL1, VENTX, and OTP) in tumor cells by integrating scRNA-seq and scATAC-seq data and further experimentally validated their roles in tumor growth." (PMID 35853872, 2022). "We injected PC-3 cells expressing GFP, HOXC5, or mir-615-3p alone, or co-expressing HOXC5 and mir-615-3p, subcutaneously into immunocompromised NSG mice and followed the tumor growth for 5 weeks." (PMID 29311615, 2018). "Comparing benign to tumour samples, HOXA6 (p = 4.26 × 10−5), HOXB6 (p = 0.001), HOXC5 (p = 4.69 × 10−5), HOXC6 (p = 3.02 × 10−28), and HOXC9 (p = 0.0001) all showed significantly greater expression in tumour samples, with HOXC6 having by far the greater fold difference." (PMID 40725480, 2025). "However, other genes, such as HOXB1, HOXC5, HOXC12, HOXD3, and HOXD12, have extremely low expression levels, suggesting that they are more expressed in normal tissue samples than in tumor samples." (PMID 39980564, 2025).
HOXC5 also shares sentences with these, for which no sentence is quoted: leukaemia (2 papers); anencephaly (1); bladder tumor (1); breast carcinoma (1); congenital heart disease (1); gastric cancer (1); kidney cancer (1); non-small cell lung carcinoma (1); Obesity (1); pancreatic cancer (1); prostate tumors (1); respiratory failure (1); thymoma (1).